GAS6 (growth arrest specific 6)
Diseases named in the same sentence as GAS6 in open-access papers (continued):
Sharing a sentence is not in itself a finding about the gene and the disease.
tumor (continued). "Finally, this article discusses the GAS6/AXL signaling pathway in the context of several immune responses such as NK cell activation, apoptosis, and tumor-specific immunity, especially PD-1/PDL-1 signaling." (PMID 34778071, 2021). "ProS is only able to bind to Tyro3 and Mertk, Gas6 can bind to all three TAM receptors (Axl > Tyro3 >>> Mertk), whereas, in a specific tumor microenvironment such as the presence of PtdSer, Mertk and Tyro3 are hyperactivated but their affinities for Gas6 are lower than Axl." (PMID 33509214, 2021). "For example, we observed the interaction between growth arrest-specific 6 (GAS6) expressed by TAMs and its cognate receptor TYRO3 expressed on the cycling tumor cells, which was reported to positively correlate with tumor growth." (PMID 34805184, 2021). "Tumor cells may induce the expression of AXL and GAS6 in monocytic myeloid-derived suppressor cells (M-MDSCs) and polymorphonuclear myeloid-derived suppressor cells (PMN-MDSCs)." (PMID 34778071, 2021). "Our data, that the silencing of hMENA/hMENAΔv6 in CAFs reduced GAS6 expression and secretion leading to the inhibition of CAF‐induced cancer cell invasiveness, are in agreement with a recent study showing that CAF‐derived GAS6 can activate AXL and promote tumor cell migration." (PMID 32909687, 2020). "At this stage, settled tumor cells enter a state of dormancy, regulated by the balance between extracellular-signal-regulated kinases (ERK) 1/2 and p38 proteins, as well as by growth-arrest-specific 6 (GAS6) and bone morphogenetic proteins (BMPs)." (PMID 32344743, 2020). "GAS6 treatment in the tumour sphere assay induced significantly larger spheres than those from cells without GAS6 and increased the number of tumour spheres from 100% (38.3 ± 6.5) to 146% (56.0 ± 9.5)." (PMID 32051483, 2020). "Activation of the axis Gas6-Axl in primary vascular cells delays senescence through PI3K/Akt/FoxO signaling, although more research is required to understand if this mechanism is relevant in tumor evolution." (PMID 32028565, 2020). "The review discusses the structure and activation of the Gas6/Axl signaling pathway, GAS6 and AXL expression patterns in the tumor microenvironment, mechanisms of Axl-mediated tumor immune response, and the role of Gas6/Axl signaling in immune cell recruitment." (PMID 32660000, 2020). "Notably, according to the pro‐invasive role of CAF‐derived GAS6 on PANC‐1, tumor cells silenced for hMENA were less invasive when treated with CAF‐CM." (PMID 32909687, 2020). "Moreover, the top three downregulated pairs in LUAD tumor cells were HLA-B and its ligand LILRB2, GAS6-AXL, and VIM-CD44." (PMID 32549766, 2020). "Immunohistochemistry showed that Gas6 was highly expressed in ESCC carcinoma tissues, but minimally expressed in adjacent normal tissues, which is consistent with findings in other tumor tissues." (PMID 32432570, 2020). "Since tumor cells secrete the ligands PROS1 and GAS6, it is hypothesized that they too contribute to this immune suppressive phenotype." (PMID 31775787, 2019). "Expression levels of AXL and GAS6 were different in two major tumor size groups, although not statistically significant (P=0.7)." (PMID 31700829, 2019). "Measurement of circulating AXL or GAS6 thus does not appear to be a viable alternative to direct determination of their expression levels in tumor tissue, at least for this patient population." (PMID 31419057, 2019). "In this study, the expression levels of GAS6, AXL, Cofilin-1, Claudin-1, as genes involved in EMT, and their relationship with clinicopathological features include; age at diagnosis, TNM staging, size and grade of tumor were investigated in EOC patients." (PMID 31700829, 2019). "Classically, their ligands protein S (PROS1) and growth arrest specific 6 (GAS6) are secreted by macrophages and cancer cells to activate PI3K, extracellular signal-regulated kinase (ERK), and NFκB pathways to promoted tumor proliferation and immune suppression." (PMID 31396227, 2019).
tumor (continued). "For example, an engineered AXL decoy receptor, which antagonizes the GAS6/AXL system by capturing GAS6, can inhibit cancer cells and tumor growth without toxicity." (PMID 31043587, 2019). "Furthermore, GAS6 inhibits the cleavage of caspase-3 and PARP to prevent apoptosis of the tumor cell." (PMID 30180883, 2018). "Below, we discuss the roles of Gas6/TAM in immune cells and VSMCs in the tumour microenvironment." (PMID 29386018, 2018). "In this section, the non-cell-autonomous roles of Gas6/TAM in the tumour microenvironment, including the involvement of immune cells and VSMCs, will be summarized." (PMID 29386018, 2018). "In this study, tumour cells did not express Gas6, whereas CD45 infiltrating-infiltrating leukocytes showed abundant expression of this protein." (PMID 29386018, 2018). "In addition, Gas6 binds to TAM receptors on natural killer (NK) cells and inhibits their anti-tumour immune effect, and Gas6 can bind to TAM receptors in vascular smooth muscle cells (VSMCs) to inhibit their apoptosis." (PMID 29386018, 2018). "Taken together, NNMT, FLI1, GAS6, lncRNA CCAT1, PDCD1LG2, and CD274, whose differential expression was confirmed, may be involved in the major mechanism of tumor-like transformation induced by chronic P. gingivalis infection." (PMID 28286742, 2017). "RSK activation by autocrine GAS6 and TAM is crucial for tumor cell survival." (PMID 28675785, 2017). "Five-year disease-free survival in patients with tumors expressing both tumor Axl and stromal Gas6 (n = 37) was significantly worse than in the both-negative group (n = 12) (21.9% vs 51.3%, p = 0.04)." (PMID 28878389, 2017). "Gas6, the ligand of TAM RTK family, is also known to act as a tumor mitogen." (PMID 29228560, 2017). "The five-year disease-free survival of the tumor Axl-negative and stromal Gas6-positive group was 50.7%, and the difference in survival between this group and both-positive group or both-negative group was not significant (p = 0.20 and 0.49, respectively)." (PMID 28878389, 2017). "Although Gas6 expression was shown to be usually higher in tumor tissue, a correlation to survival was not confirmed throughout different tumor entities." (PMID 27486820, 2016). "5-FU treatment of the CRC tumor cell line HCT116 did not lead to any changes in Gas6 expression, while Gas6 expression was increased in the macrophage cell line J774A.1 upon 5-FU treatment (p < 0.0005)." (PMID 27486820, 2016). "This stems from the fact that Vit-K-dependent γ-carboxylation of Gas6/Pros1 is widely, if not ubiquitously, expressed in non-hepatic cells that include many of the cells that express Gas6 in the tumor microenvironment." (PMID 27916840, 2016). "Given that KRASG12D non-cell-autonomously regulates growth factor production from PSCs (e.g., IGF1 and GAS6), we hypothesized that KRASG12D-activated PSCs initiate a reciprocal signaling axis back in the tumor cells." (PMID 27087446, 2016). "To assess if the ligand Gas6 or its TAM receptors are differentially expressed within tumors in comparison to normal intestinal mucosa of the same patients, we performed qPCRs from 200 primary tumors with different tumor stages (UICC stage I–IV)." (PMID 27486820, 2016). "The number of Gas6 expressing cells within the tumor did not correlate with tumor stage or i.e. lymph node metastases (not shown)." (PMID 27486820, 2016). "Using a transwell assay we found that Gas6 did not increase migration of tumor cells, however invasion was significantly increased by Gas6 stimulation (p < 0.05)." (PMID 27486820, 2016). "GAS6 but not AXL was associated with lymph nodes status (p < 0.05) and consequently with tumour stage (p < 0.05) showing a higher expression in more advanced disease (data not shown)." (PMID 25966280, 2015). "Specifically, patients with low Axl and high Gas6 mRNA levels in the tumor have better prognosis than those without." (PMID 25344858, 2014).
tumor (continued). "Estimations of the immunological balance of Gas6 and CD68 may supplement other established tumour markers, but their impact on survival will require confirmation in prospective studies." (PMID 21794149, 2011). "The Gas6-AXL pathway is involved in tumor stimulating actions such as stimulating growth and invasion as well as in anti tumor actions, increasing leukocyte transmigration from vessels important in tumor targeting." (PMID 19558675, 2009). "All the specimens were positive for ribosomal 18S; however, six samples were negative for Gas6 mRNA expression and there was a wide variation in the Gas6 mRNA levels in the primary tumour cohort." (PMID 18283315, 2008). "Our results revealed a regulatory axis by which elevated GAS6 secreted by reactive astrocytes activates the receptor AXL on the surface of BrM-CSCs, which induces the transcription of CD146, highlighting the role of the TME in engaging the mesenchymal transformation of CTCs and tumor angiogenesis." (PMID 41356185, 2026). "Gas6 binds not only to the receptor tyrosine kinase AXL in PDAC cells, activating the Gas6/AXL signaling pathway and promoting epithelial‒mesenchymal transition (EMT), but also to the receptor tyrosine kinase AXL in NK cells, inhibiting immune cell activation and accelerating tumor cell metastasis." (PMID 41281760, 2025). "The AXL ligand GAS6 is secreted by cancer-associated fibroblasts in NSCLC and by tumour-associated macrophages in bone marrow; however, its secretion within NB tumours has not yet been established." (PMID 41511287, 2025). "The Gas6/AXL pathway regulates angiogenesis, immune-related molecular markers, and the secretion of certain cytokines (MHC-I, PD-L1, IL-4, CCL3-5, and G-CSF) in the tumor microenvironment, and it also regulates the functions of various immune cells (NK, DC, M2, and Treg)." (PMID 40524208, 2025). "Hence, batiraxcept can inhibit GAS6-mediated AXL signaling to exert anti-tumor effects." (PMID 39062902, 2024). "In addition, GAS6-CAR-T cells could significantly reduce AXL and CK19 double-positive tumor cells, as well as AXL and CD68 double-positive macrophages." (PMID 37475048, 2023). "Therefore, interactions among the tumor, host immune cells, and abnormal physiological factors in the TME may upregulate AXL and Gas6, thus promoting a pro-tumor microenvironment." (PMID 37265798, 2023). "Interestingly, Gas6/Axl signaling components are upregulated in the injured liver during HSC activation to myofibroblasts to prevent apoptosis, during malignant progression of neoplastic hepatocytes, and are drivers of tumor angiogenesis." (PMID 37532736, 2023). "Moreover, we only found an increase of Gas6 expressing neutrophils in tumour-bearing livers, but not in tumour-free lung tissues, suggesting Gas6 expressing neutrophils preferentially accumulate at the metastatic tumour site." (PMID 35022267, 2022). "Furthermore, the unique tumor microenvironmental conditions may modulate AXL and GAS6 expression in both tumor and immune cells to promote aggressive and pro-tumorigenic features." (PMID 34778071, 2021). "Thus, the GAS6/AXL signaling is established and tumor cell dormancy is initiated." (PMID 34212564, 2021). "In this study, tumor-derived Gas6 protein did not strongly correlate to Axl expression." (PMID 32352034, 2020). "Herein, we evaluate the neurotropism of ZIKV relative to the receptor tyrosine kinase AXL and its ligand Gas6 in viral entry and the RNA-binding protein Musashi-1 (MSI1) in replication which are also overexpressed in GBM, suggesting its potential for specific targeting of the tumor." (PMID 31824472, 2019). "Among three TAM member, AXL, both growth arrest-specific gene 6 (GAS6)-dependent and (GAS6)-independent, can promote many downstream signaling pathways and transcription factors regulating cell survival, growth, EMT, metastasis, and tumor microenvironment in cancer cells." (PMID 31043587, 2019).
tumor (continued). "Furthermore, tumor-related genes including GAS6 and PD-L1 that possibly act as key regulators in transformation from non-cancerous to tumor cells were upregulated as a reaction to long-term exposure of P. gingivalis." (PMID 30837987, 2019). "In addition, the Gas6 expression level in these leukocytes was found to be specifically upregulated after entering the tumour, as these cells do not secrete Gas6 while circulating in the blood or residing in the bone marrow." (PMID 29386018, 2018). "In combining results of bioinformatics analyses and validation assays, tumor-related genes such as NNMT, FLI1, GAS6, lncRNA CCAT1, PDCD1LG2, and CD274 may be considered as the key regulators in tumor-like transformation in response to long-time exposure of P. gingivalis." (PMID 28286742, 2017). "Here, we extended these studies to investigate the requisite role of PS with respect to Gas6-mediated TAM activation, as well as inquiring whether PS externalization on apoptotic cells, calcium-stressed cells, or tumor exosomes have different capabilities to activate TAMs." (PMID 29176978, 2017). "However, secretion of Gas6 in the tumor stromal microenvironment in humans has not been previously reported." (PMID 28878389, 2017). "Gas6 or its receptors were not differentially expressed according to UICC tumor stages." (PMID 27486820, 2016). "Altogether, these results indicate that Gas6 is able to induce proliferation, colony formation and invasion of CRC tumor cells and suggest that within CRC tumors, Gas6 secreted either by tumor cells or macrophages, might regulate these processes in an autocrine or paracrine manner, respectively." (PMID 27486820, 2016). "Additionally, it is becoming increasingly clear that the Gas6/Axl signaling axis also impacts non-neoplastic cell populations, which may be of particular relevance when viewed in the context of the tumor microenvironment." (PMID 34576116, 2021). "GAS6, AXL, and Cofilin-1 are overexpressed, but because of tissue-specific functions of claudins family, Claudin-1 may have a different role in various cancers; depending on the origin of cancer cells and the adjacent tumor microenvironment, it may increase or decrease in various cancers." (PMID 31700829, 2019). "Here, we first observed reduced NF-kB activation in MM cells lacking GAS6 and after treatment with GAS6 depleted-BMSC-CM, thus revealing that TAM receptor signaling controls NF-kB activity in these tumor cells." (PMID 35967396, 2022). "Also, we could not show a significant difference in OS in Gas6+ versus Gas6− tumor patients." (PMID 35760058, 2022). "SRC proto-oncogene nonreceptor tyrosine kinase is a direct target of GAS6/AXL signaling, and once activated, it induces the MET proto-oncogene, thereby regulating EMT and ccRCC tumor metastasis." (PMID 35659268, 2022). "In cancer settings, the activation of TAM receptors by GAS6 was shown in several tumor models, however the role of PROS1 in oncogenic signaling and tumor biology has not been extensively investigated." (PMID 28118606, 2017). "Gas6 negatively regulates AXL expression levels in general, but not in hypoxic environments such as in a tumor or in bone." (PMID 26762579, 2016). "He presented clinical data showing, that RTK-AXL is mainly expressed in pseudo-palisades and GFAP positive tumor cells, whereas the specific ligand of RTK-AXL Gas6 is expressed in hypoxic border zone but not in pseudo-palisades." (PMID 26848524, 2016). "The fact that addition of an antibody enhances the suppressive effect of HiB5 and ST14A on tumor growth gives hints that the suppressive effect of these NPC is not due to their secretion of TPT1, CD81 and CXCL1, Gas6/Axl but to other factors." (PMID 19558675, 2009). "Although persistent AXL/GAS6 co-overexpression and acquired MERTK and KDR overexpression did not accelerate tumor xenograft growth rate, other concurrent phenotypic changes might nonetheless bear on disease progression." (PMID 34292953, 2021).
cancer (216 papers, 2005 to 2026). A tumor composed of atypical neoplastic, often pleomorphic cells that invade other tissues. "Cancer-associated fibroblasts (CAFs) can enhance the aggressiveness of GC cells by activating the GAS6/AXL signaling axis." (PMID 40455337, 2025). "In conclusion, comprehensive studies across various cancers are needed to unravel the precise molecular mechanisms underlying GAS6/AXL crosstalk with VEGFR and its regulation of angiogenic programs." (PMID 39924521, 2025). "AXL, a TAM receptor tyrosine kinase (RTK), and its ligand growth arrest-specific 6 (GAS6) are implicated in cancer metastasis and drug resistance, and cellular entry of viruses." (PMID 35622156, 2022). "The Gas6/Axl signaling pathway has been implicated to promote progression, metastasis, immune evasion, and therapeutic resistance in many cancer types." (PMID 34576116, 2021). "It is worth noting that Gas6 is produced and released from cancer-associated fibroblasts and M2 macrophages, suggesting a positive feedback loop that drastically reinforces the immunosuppressive environment in tumors." (PMID 33562150, 2021). "The TAM (Tyro3, Axl, MerTK) subfamily of receptor tyrosine kinases (RTKs) and their ligands, Gas6 and protein S (ProS1), are implicated in tumorigenesis and chemoresistance in various cancers." (PMID 32664510, 2020). "In this study, we investigated the mechanism underlying the anti-cancer effects of cabozantinib through the regulation of GAS6-AXL and HGF-MET signaling." (PMID 32055714, 2020). "Numerous studies have suggested that macrophage-derived Gas6 interacts with Axl to promote cancer progression, and Axl has been associated with poor clinical outcome." (PMID 32352034, 2020). "In conclusion, we have shown that ProS1 is the most prominent functional ligand for Tyro3 RTK in human cancer cells and that it is linked to the Erk signalling pathway, distinct from the more well-characterised Gas6-Axl-Akt signalling axis." (PMID 31766614, 2019). "Investigations of the underlying mechanisms indicate the potential of targeting Gas6/TAM as cancer therapy." (PMID 29386018, 2018). "The underlying mechanisms of Gas6/TAM involvement in cancer cell survival should also be studied in the future with regard to genes mutated or upstream regulators." (PMID 29386018, 2018). "Recently, publications point out that AXL‐activating ligand GAS6 is also linked to cancer drug resistance." (PMID 28675785, 2017). "In recent years, overexpression of TAM receptors and Gas6 has been reported in a wide range of human cancers, an axis that is associated with aggressive cancer phenotypes, emergence of drug resistance, immune escape, and overall poor patient survival." (PMID 28272423, 2017). "Overexpression of TAMs and their major ligand Growth arrest-specific factor 6 (Gas6) is associated with more aggressive staging of cancers, poorer predicted patient survival, acquired drug resistance and metastasis." (PMID 28272423, 2017). "The Axl (Gas6) axis has been reported in a multitude of human cancers, and more frequently associated with EMT and metastasis than other TAMs." (PMID 27595981, 2016). "Notably, methylmalonic acid (MMA), a metabolite recently linked to cancer cell proliferation and aggressiveness, was significantly accumulated in GAS6-treated cells, as validated by LC/MS." (PMID 41034991, 2025). "TAM receptors and Gas6 have been studied in different types of cancers and Gas6/TAM-related signaling pathways are associated with the activation of standard proliferative pathways (including MEK/ERK and PI3K/AKT), implicated in cell proliferation, growth and survival." (PMID 38298195, 2024). "Furthermore, by differential gene expression analysis on total cancer cells in the 2 cultures, we identified several dormancy-associated genes such as Cst6, Mgp, Mme, Gas6, etc. to be up-regulated in the TSO culture compared to monotypic culture." (PMID 37699010, 2023).